OTC (ornithine transcarbamylase)
Diseases named in the same sentence as OTC in open-access papers (continued):
Sharing a sentence is not in itself a finding about the gene and the disease.
hemophilia (2 papers, 2006 to 2017). Hemophilia is a genetic disorder characterized by spontaneous hemorrhage or prolonged bleeding due to factor VIII or IX deficiency. "Some disorders, such as hemophilia, require minimal activity to correct the associated bleeding propensity, while others, such as the proximal urea cycle disorder ornithine transcarbamylase (OTC) will require more activity, and larger numbers of cells corrected, to normalize metabolism." (PMID 28238287, 2017).
leukemia (2 papers, 2015 to 2018). A malignant (clonal) hematologic disorder, involving hematopoietic stem cells and characterized by the presence of primitive or atypical myeloid or lymphoid cells in the bone marrow and the blood. "The advent of viral therapy brought concerns about its safety when retroviral integration causing activation of the proto-oncogene LMO2 led to leukemia in patients treated for SCID and after the death of a patient with ornithine transcarbamylase deficiency treated with adenoviral gene therapy." (PMID 26280277, 2015).
liver disease (2 papers, 2024 to 2025). "We previously developed the here applied liver disease model generating multiple patient‐derived hiPSC‐Heps of several OTC‐deficient patients." (PMID 40421674, 2025). "tried to correct a metabolic liver disease in mice (ornithine transcarbamylase [OTC] deficiency) by intravenously infusing two AAVs, one expressing Cas9 and the other expressing a guide RNA, and the donor OTC DNA sequence." (PMID 38488469, 2024).
medulloblastoma (2 papers, 2017 to 2022). A malignant, invasive embryonal neoplasm arising from the cerebellum. "In medulloblastoma MYC (associated with a poor prognosis) had a positive correlation with FDR <0.05, for both the OTC and ARG2 oncogenic and hallmark gene lists." (PMID 28969007, 2017).
melanoma (2 papers, 2018 to 2020). A malignant, usually aggressive tumor composed of atypical, neoplastic melanocytes. "The tumour had absent expression of the recycling enzymes argininosuccinate synthetase (ASS) and ornithine transcarbamylase (OTC) indicating a state of arginine auxotrophy, which was reconfirmed by immunohistochemistry, and validation in a larger cohort of melanoma tumour samples." (PMID 29776373, 2018).
osteosarcoma (2 papers, 2017 to 2020). A usually aggressive malignant bone-forming mesenchymal neoplasm, predominantly affecting adolescents and young adults. "MTOR signaling, a known downstream effector of amino acid metabolism and a target for novel agents in relapsed paediatric tumours, was enriched within osteosarcoma for both OTC and ARG2." (PMID 28969007, 2017). "Although osteosarcomas expressed ASS, expression of OTC and ASL were lower in comparison." (PMID 28969007, 2017).
sarcoma (2 papers, 2017 to 2021). A usually aggressive malignant neoplasm of the soft tissue or bone. "The analysis above indicates that the major paediatric sarcomas universally express SLC7A1, ARG2, and ASS, but have low OTC expression." (PMID 28969007, 2017). "Gene set enrichment was carried out for all sarcoma and CNS tumour subtypes, using pre-ranked gene lists correlating with ARG2 and OTC." (PMID 28969007, 2017). "Although ASS was universally expressed, OTC was significantly underexpressed in all three subgroups of sarcomas and absent of very low in all CNS tumours." (PMID 28969007, 2017).
short bowel syndrome (2 papers, 2024 to 2025). "Finally, enrichment analysis showed that several DOR-associated metabolites are implicated in the pathogenesis of various human disorders, including argininosuccinic aciduria, short bowel syndrome, and ornithine transcarbamylase deficiency." (PMID 39857797, 2025). "Furthermore, the enrichment analysis indicated that numerous metabolites associated with DOR were implicated in the pathogenesis of diverse human disorders, such as argininosuccinic aciduria (ASL), short-bowel syndrome (permanent intestinal failure), and ornithine transcarbamylase deficiency." (PMID 38535303, 2024).
steatosis (2 papers, 2021 to 2022). Increased lipid within the cytoplasm of cells. "Interestingly, steatosis in primary hepatic cells was also associated with OTC and CPS1 promoter hypermethylation, decreased OTC and CPS1 gene expression, and ammonia generation." (PMID 33490737, 2021).
tyrosinemia (2 papers, 2022 to 2023). An autosomal recessive inherited metabolic disorder caused by mutations in the FAH, HPD, and TAT genes. "In other studies, it can be used to treat rare diseases such as ornithine transcarbamylase (OTC) deficiency and hereditary tyrosinemia." (PMID 35163260, 2022).
Alagille syndrome (1 paper, 2021). "Moreover, Alpha-1-antitrypsin and Ornithine transcarbamylase functions should also be assessed to evaluate the potential use of our hepatic organoids as models to study the pathologies of α1-antitrypsin deficiency and Alagille syndrome patients." (PMID 34943788, 2021).
anorexia nervosa (1 paper, 2024). A disorder most often seen in adolescent females characterized by a refusal to maintain a minimally normal body weight, an intense fear of gaining weight, a disturbance in body image, and, in postmenarcheal females, the development of amenorrhea. "The patient was diagnosed with ornithine transcarbamylase (OTC) deficiency (hyperammonemia type II), following an initial diagnosis of pervasive developmental disorder, selective mutism, and anorexia nervosa." (PMID 38673463, 2024).
breast tumors (1 paper, 2012). "Of the loci evaluated for LOH in breast tumors, the Arg3 homolog, OTC, displayed LOH in 30% of breast tumors, while the Tsa1 homolog, PRDX1, was lost in 26% of tumors." (PMID 22347400, 2012).
cervical cancer (1 paper, 2020). A primary or metastatic malignant neoplasm involving the cervix. "OTC expression, however, was detected using normal human liver cDNA library as a template, indicating that the undetectable OTC expression in the cervical cancer cells was due to deficient expression." (PMID 33050217, 2020). "In order to study the effect of OTC expression on the susceptibility of cervical cancer cells towards BCA-M treatment, HeLa cells were transduced with OTC expression construct using recombinant adenovirus and confirmed with OTC expression using Western blotting." (PMID 33050217, 2020). "Arg I and OTC expressions were undetectable in all five human cervical cancer cell lines, while the ASS gene was expressed only in three cell lines including ME-180, CC3 and HeLa." (PMID 33050217, 2020). "Furthermore, the results were consistent with OTC protein expressions determined using Western blotting, where it was undetectable in all five cervical cancer cells but present in the BJ normal human fibroblast." (PMID 33050217, 2020).
colorectal tumors (1 paper, 2018). "Finally, we analyzed gene expression datasets using the online platforms CancerMA and Oncomine21,22 and we confirmed downregulation of the OTC gene expression in colorectal tumors." (PMID 30108309, 2018).
cryptorchidism (1 paper, 2021). The failure of one or both testes of a male fetus to descend from the abdomen into the scrotum during the late part of pregnancy. "Patient p18, who had an exon 4 deletion in the OTC gene, presented cryptorchidism." (PMID 34829455, 2021).
developmental arrest (1 paper, 2014). "It seems as if the expression of CPS1, OTC, ASL, NAGS and GLUD1 in dogs with CPSS has come to a developmental arrest which prevented them to normalize after closure of the shunt." (PMID 24945279, 2014).
Fibrolamellar carcinoma (1 paper, 2023). "Fibrolamellar carcinoma and adenomyomatosis samples presented increased expression of Aurora kinase A, c-MYC, and ornithine decarboxylase when compared to normal liver, while ornithine transcarbamylase was decreased." (PMID 36788919, 2023).
gangliosidosis (1 paper, 2020). A group of autosomal recessive lysosomal storage disorders marked by the accumulation of gangliosides. "Diagnoses included nonketotic hyperclycinemia (NKH) (n = 2), ornithine transcarbamylase deficiency (OTC) (n = 3), propionic academia (n = 1), congenital disorder of glycosylation 1a (CDG1a) (n = 1), D‐bifunctional protein deficiency (DBP) (n = 1), and GM1 Gangliosidosis (n = 1)." (PMID 32495504, 2020).
hydronephrosis (1 paper, 2024). Collection of urine in the renal pelvis that results in dilatation of the renal pelvis and calyces. "Therefore, we suggest that Otc mutations that cause OTC dysfunction are a congenital factor in the development of hydronephrosis." (PMID 39000307, 2024). "Gene expression analysis of the liver suggested that dysfunction of ornithine transcarbamylase (OTC), encoded by the X chromosome gene Otc and involved in the urea cycle, may contribute as a congenital factor in hydronephrosis." (PMID 39000307, 2024). "This study suggests that dysfunction of OTC, which regulates the urea cycle in the liver, may be a congenital factor causing hydronephrosis." (PMID 39000307, 2024). "Therefore, to determine whether the hydronephrosis-like pathology frequently observed in this study was related to Otc, we examined the gene expression profiles of the liver, which is the primary OTC-expressing organ that carries out the urea cycle." (PMID 39000307, 2024).
influenza infection (1 paper, 2014). "A previous study examining the effect of influenza infection on CPS1 and OTC activities in WT B6 mice showed appreciable reductions in CPS1 (12%) and OTC (17%) enzyme activities." (PMID 24271778, 2014).
Iron deficiency (1 paper, 2020). "In the current study, the result showed the hepatic mRNA expression of OTC and AS were induced in the iron deficiency group." (PMID 32764239, 2020). "Iron deficiency increased the hepatic mRNA expression of cyp7a1, OTC, and AS (p < 0.05)." (PMID 32764239, 2020).
neuroblastoma (1 paper, 2025). Neuroblastoma (NB) is the most common solid, extracranial childhood tumor. "While ASS1 expression did not correlate with BCT-100 IC50 in neuroblastoma cell lines, upregulation of ASS1/ASL/OTC was observed in some BCT-100 treated Th-MYCN tumors." (PMID 40813699, 2025).
orotic aciduria (1 paper, 2023). An extremely rare autosomal recessive inherited disorder caused by mutations in the UMPS gene. "Similarly, orotic acid in urine is a biomarker of the following metabolic diseases: Ornithine Transcarbamylase Deficiency, N-Acetylglutamate Synthase Deficiency, and Orotic Aciduria." (PMID 37627634, 2023).
pancreatic cancers (1 paper, 2024). "Our findings also indicated that OTC deficiency is more prevalent than ASS1 in human pancreatic cancer." (PMID 39570001, 2024). "In line with our own cohort, pancreatic cancers showed minimal expression of both OTC and ASS1 compared with other cancer types." (PMID 39570001, 2024). "The deficiency in OTC and ASS1 in human pancreatic cancer facilitates this combination approach, which also serves as a predictive biomarker for the response to this novel therapeutic strategy." (PMID 39570001, 2024). "As low ASS1 and OTC expressions were shown to facilitate the response to the combination treatment, we then investigated the clinical relevance of this therapeutic approach by analyzing our in-house patient cohort with pancreatic cancer." (PMID 39570001, 2024). "Additionally, we evaluated the expression levels of ASS1 and OTC in pancreatic cancer and their correlation with the efficacy of the combination treatment." (PMID 39570001, 2024). "From our in-house cohort and online database analysis, we found that the majority of the patients with pancreatic cancer exhibited deficiencies in both ASS1 and OTC enzymes, suggesting that the combination of arginine deprivation and canavanine could be particularly effective in these patients." (PMID 39570001, 2024). "IHC staining was performed on 61 pancreatic cancer specimens, revealing that a majority of patients exhibited low or no expression of ASS1 and OTC enzymes." (PMID 39570001, 2024). "Notably, 57.3% of the patients lacked both OTC and ASS1 enzymes, indicating most of the pancreatic cancers are arginine-auxotrophic." (PMID 39570001, 2024).
pancreatic tumors (1 paper, 2024). "Our findings suggest heightened susceptibility of pancreatic tumors deficient in arginine biosynthesis enzymes ASS1 and OTC." (PMID 39570001, 2024). "Our findings also suggested that pancreatic tumors lacking the key enzymes in arginine biosynthesis, argininosuccinate synthetase 1 (ASS1) and ornithine transcarbamylase (OTC), were more susceptible to the treatment." (PMID 39570001, 2024).
respiratory infection (1 paper, 2023). "In one published case of severe ornithine transcarbamylase (OTC) deficiency, HM was discontinued at 1.5 months due to hyperammonaemia associated with a respiratory infection." (PMID 37630757, 2023).
tumor (28 papers, 2014 to 2025). "Therefore, low OTC expression may enable tumor cells to increase ammonia accumulation, representing a loss of function of the tumor-specific metabolism of OTC." (PMID 35327967, 2022). "These arginine auxotrophic tumor cells lack either argininosuccinate synthase 1 (ASS1) or ornithine carbamoyltransferase (OTC) expression, and thus interrupt the normal urea cycle." (PMID 31427725, 2019). "Arginine deprivation did not trigger an upregulation of ASS or ASL, often observed in other tumour cell lines, or induction of OTC transcription." (PMID 24987688, 2014). "Whether the differential behavior of CZ017’s OTC is related to its distinct tumor subtype, more advanced stage, and/or the influence of neoadjuvant therapy requires further studies." (PMID 40209948, 2025). "Profiling tumor gene expression of ASS1 and OTC before treatment could predict tumor response to arginine depletion with arginine-depleting enzymes." (PMID 37445845, 2023). "Thus, normal cells which lack OTC can become toxic while tumor cells which lack both ASS and OTC are more sensitive." (PMID 25749046, 2015). "On the contrary, the OTC status, whether positive or negative, were found not to associate with tumour response or OS." (PMID 33856599, 2021). "For instance, we recently demonstrated the increase in vivo persistence and efficacy of anti-CD33 CAR-T metabolically enhanced by inserting ASS1 and OTC expression domains such that these cells could re-synthesized arginine from citrulline discarded by the tumor cells." (PMID 34094976, 2021). "The results showed that the expression of FGA, OTC, and CTH in the tumor tissues of patients with CCA is significantly lower than that in normal tissues, but that the expression of MMP11 is significantly higher than that in normal tissues." (PMID 36300097, 2022). "One important characteristic of tumor cells is their auxotrophic state for arginine due to defects into the biosynthesis enzyme machinery, specifically ASS, ASL, and ornithine transcarbamylase (OTC)." (PMID 35159363, 2022). "All patients must have freshly obtained tumour biopsies or archival tumour tissue obtained within 6 months prior to commencement of treatment for analyses of protein expression of ASS and OTC." (PMID 33856599, 2021). "Adaptive expression of urea cycle enzymes ARG1/2, OTC, ASL and regulators like NAT10, which stabilizes ATF4 mRNA via ac4C modification to upregulate asparagine synthetase (ASNS) optimizing nitrogen utilization for tumor proliferation." (PMID 41179661, 2025). "Subclusters 2 and 8 exhibited high expression of the metabolic factors CYP3A4, OTC, PCK1 and TAT, suggesting that these genes may be involved in tumor cell metabolic reprogramming events." (PMID 38927691, 2024). "For patients with available IHC results, 10 patients with ASS-negative tumour had OS of 35 weeks (95% CI: 8.3–78.0 weeks) vs. 15.14 weeks (95% CI: 13.4–15.1 weeks) in 3 with ASS-positive tumour; expression of OTC did not correlate with treatment outcomes." (PMID 33856599, 2021). "OTC and ASS expressions in tumour tissues were assessed using IHC." (PMID 33856599, 2021).
tumor (continued). "The influence of TME on tumor metabolic reprogramming could also be inferred from activated GNG-fueled synthesis of purine nucleotides in all ER+/PR+/HER2- CA OTC, which was absent from 2D MCF-7 cells with the same genotype." (PMID 40209948, 2025). "An absence of OTC may suggest that tumours use ornithine for polyamine synthesis and not arginine regenertation." (PMID 28969007, 2017). "Notably, no expression of OTC was detected in tumor isolated from rhArg1peg5000 treated animals." (PMID 30108309, 2018). "Regardless of the tumor genotype or stage, Gln-fueled GNG was activated in BC OTC to drive nucleotide synthesis." (PMID 40209948, 2025).